ENSG00000241690 (novel protein)
Gene: Protein-coding gene on chromosome 20 (2,814,968 to 2,818,066, forward strand). Ensembl gene ENSG00000241690.
Genetic constraint (gnomAD): Loss-of-function variants: 14 observed, 13.95 expected, observed/expected ratio (o/e) 1, 90% interval 0.66 to 1.56. Missense variants: 351 observed, 309.04 expected, observed/expected ratio (o/e) 1.14, 90% interval 1.04 to 1.24. Synonymous variants: 126 observed, 133.57 expected, observed/expected ratio (o/e) 0.94, 90% interval 0.81 to 1.09.